MCMDC2 (minichromosome maintenance domain containing 2)
Description:
Plays an important role in meiotic recombination and associated DNA double-strand break repair.
Synonyms: C8orf45; FLJ25692
Tractability: No criterion of Open Targets' tractability assessment is met for any kind of drug.
Gene: Protein-coding gene on chromosome 8 (66,870,749 to 66,922,048, forward strand). Ensembl gene ENSG00000178460.
Subcellular location (Human Protein Atlas): Actin filaments
Gene Ontology:
Molecular function: protein binding; ATP binding; DNA binding
Biological process: double-strand break repair via break-induced replication
Genetic constraint (gnomAD): Loss-of-function variants: 36 observed, 58 expected, observed/expected ratio (o/e) 0.62, 90% interval 0.47 to 0.82. The upper end of that interval is the gene's LOEUF score, 0.82, which puts it in group 3 of 6, group 1 being the genes least tolerant of losing a copy. Missense variants: 550 observed, 663.58 expected, observed/expected ratio (o/e) 0.83, 90% interval 0.77 to 0.89. Synonymous variants: 208 observed, 232.85 expected, observed/expected ratio (o/e) 0.89, 90% interval 0.8 to 1.
Homologues: Orthologues: chimpanzee MCMDC2 (99% identical), macaque MCMDC2 (98% identical), rabbit MCMDC2 (93% identical), dog MCMDC2 (90% identical), mouse Mcmdc2 (85% identical), guinea pig MCMDC2 (85% identical), rat Mcmdc2 (85% identical), zebrafish MCMDC2 (50% identical), tropical clawed frog mcmdc2 (46% identical). Paralogues in human: MCM9 (18% identical), MCM8 (17% identical), MCM4 (16% identical), MCM7 (15% identical), MCM3 (15% identical), MCM6 (15% identical), MCM2 (14% identical), MCM5 (14% identical).